ZNF195 (zinc finger protein 195)
Description:
May be involved in transcriptional regulation.
Synonyms: ZNFP104; HRF1
Tractability: PROTAC: UniProt records ubiquitination sites on it; ubiquitination databases record sites on it.
Gene: Protein-coding gene on chromosome 11 (3,339,261 to 3,379,222, reverse strand). Ensembl gene ENSG00000005801.
Subcellular location: Nucleus
Subcellular location (Human Protein Atlas): Nucleoplasm; Cytosol
Pathways (Reactome):
Gene expression (Transcription): Generic Transcription Pathway
Gene Ontology:
Molecular function: DNA-binding transcription factor activity, RNA polymerase II-specific; RNA polymerase II cis-regulatory region sequence-specific DNA binding; zinc ion binding
Biological process: regulation of DNA-templated transcription; regulation of transcription by RNA polymerase II
Cellular component: nucleus
Genetic constraint (gnomAD): Loss-of-function variants: 8 observed, 16.59 expected, observed/expected ratio (o/e) 0.48, 90% interval 0.28 to 0.87. The upper end of that interval is the gene's LOEUF score, 0.87, which puts it in group 3 of 6, group 1 being the genes least tolerant of losing a copy. Missense variants: 543 observed, 702.8 expected, observed/expected ratio (o/e) 0.77, 90% interval 0.72 to 0.83. Synonymous variants: 206 observed, 243.93 expected, observed/expected ratio (o/e) 0.84, 90% interval 0.75 to 0.95.
Homologues: Orthologues: chimpanzee ZNF195 (99% identical), macaque ZNF195 (95% identical). Paralogues in human: ZNF429 (45% identical), ZNF728 (43% identical), ZNF595 (42% identical), ZNF254 (42% identical), ZNF724 (42% identical), ZNF726 (42% identical), ZNF85 (42% identical), ZNF841 (41% identical), ZNF93 (41% identical), ZNF708 (41% identical), ZNF43 (41% identical), ZNF267 (40% identical), and 164 more.
Diseases named in the same sentence as ZNF195 in open-access papers:
ZNF195 is named in the same sentence as 6 diseases in open-access papers, as found by Europe PMC text mining. Sharing a sentence is not in itself a finding about the gene and the disease. The quoted sentences say what the papers report.
head and neck squamous cell carcinoma (2 papers, 2019 to 2021). A squamous cell carcinoma that arises from any of the following anatomic sites: lip and oral cavity, nasal cavity, paranasal sinuses, pharynx, larynx, and salivary glands. "ZNF195 is one of the most significant survival-associated genes in bladder cancer and has been previously reported as a biomarker for gemcitabine sensitivity in head and neck squamous cell carcinoma." (PMID 34638319, 2021). "The expression of ZNF195 was closely related to gemcitabine sensitivity in head and neck squamous cell carcinoma (HNSCC) and decreased in the low level of oxygen in first trimester human trophoblast cells." (PMID 31455417, 2019).
cutaneous T cell lymphoma (1 paper, 2019). "Previous studies have shown that ZNF195 is related to various cancers, such as cutaneous T cell lymphoma." (PMID 31455417, 2019).
Wilms tumor (1 paper, 2021). An embryonal neoplasm characterized by the presence of epithelial, mesenchymal, and blastema components. "ZNF195 is located near the centromeric border of chromosome 11p15.5, next to an imprinted domain that is associated with maternal-specific loss of heterozygosity in Wilms' tumors." (PMID 34863158, 2021).
cancer (3 papers, 2019 to 2021). A tumor composed of atypical neoplastic, often pleomorphic cells that invade other tissues. "Our results demonstrate that ZNF195 is significantly positively associated with higher KIRC grade and stage, and high ZNF195-expressing tumors possess cancer stemness characteristics, although the level of ZNF195 does not correlate with patient prognosis." (PMID 34638319, 2021).
ZNF195 also shares sentences with these, for which no sentence is quoted: bacterial disease (1 paper); bladder cancer (1).